BMAL1 (basic helix-loop-helix ARNT like 1)
Diseases named in the same sentence as BMAL1 in open-access papers (continued):
Sharing a sentence is not in itself a finding about the gene and the disease.
dermatitis (3 papers, 2010 to 2022). An inflammatory process affecting the skin. "Further, loss of Bmal1 gene or chronic jet lag sensitized mice to P. acnes-induced skin inflammation." (PMID 35414779, 2022). "We next investigated the role of BMAL1 in P. acnes-induced skin inflammation using Bmal1 knockout (KO) mice." (PMID 35414779, 2022). "It was thus proposed that Bmal1 restrained P. acnes-induced skin inflammation via its target REV-ERBα, which acts on the NF-κB/NLRP3 axis to repress inflammation." (PMID 35414779, 2022). "Mechanistically, Bmal1 regulated P. acnes-induced skin inflammation via its target REV-ERBα, which acts on the NF-κB/NLRP3 axis to repress inflammation." (PMID 35414779, 2022). "Mechanistically, Bmal1 regulates P. acnes-induced skin inflammation via its target REV-ERBα, which acts on the NF-κB/NLRP3 axis to repress inflammation." (PMID 35414779, 2022). "We also observed a high overlap (75%) between P. acnes- and Bmal1-associated enriched pathways, supporting regulation of P. acnes-induced skin inflammation by Bmal1." (PMID 35414779, 2022). "Based on transcriptomic analyses, we have demonstrated that NF-κB signaling and NLRP3 inflammasome pathway were involved in P. acnes-induced and Bmal1-regulated skin inflammation." (PMID 35414779, 2022). "Because REV-ERBα is a known inflammatory modulator, our findings suggest a potential role of BMAL1 in P. acnes-induced skin inflammation." (PMID 35414779, 2022). "Taken together, Bmal1 regulates P. acnes-induced skin inflammation via the NF-κB/NLRP3 axis." (PMID 35414779, 2022). "Therefore, we propose that Bmal1 restrains P. acnes-induced skin inflammation via its target REV-ERBα, which acts on the NF-κB/NLRP3 axis to repress inflammation." (PMID 35414779, 2022). "CLOCK and BMAL1 proteins were recently implicated in the regulation of the hair cycle and hair follicle stem cell proliferation, thus, CLOCK deficiency can affect skin epithelium homeostasis, which also can contribute to the development of dermatitis." (PMID 21149897, 2010). "CLOCK and BMAL1 are involved in the control of memory and adaptation to novelty therefore, at this time we cannot exclude the possibility that increased dermatitis in Clock−/− mice is a consequence of changes in behavioral patterns; the detailed study of Clock−/− behavior is currently in progress." (PMID 21149897, 2010). "Because the NF-κB/NLRP3 axis is also involved in BMAL1 regulation of P. acnes-induced skin inflammation, we thus have tested whether REV-ERBα has a mediating role in the regulation of skin inflammation by BMAL1." (PMID 35414779, 2022). "Given that the NF-κB/NLRP3 axis is also involved in BMAL1 regulation of P. acnes-induced skin inflammation, we hypothesized that REV-ERBα may mediate the regulation of skin inflammation by BMAL1." (PMID 35414779, 2022). "Although Bmal1−/− mice have a high frequency of corneal inflammation, we have never detected dermatitis in these mice." (PMID 21149897, 2010).
diabetic cardiomyopathy (3 papers, 2017 to 2025). Diabetic cardiomyopathy is a disorder of the heart muscle in people with diabetes. "In diabetic cardiomyopathy, BMAL1 overexpression enhanced BMAL1/BCL2 binding, which suppressed IP3R activity, reduced mitochondrial Ca2+ overload, and attenuated subsequent apoptosis." (PMID 41142939, 2025). "Given this evidence, we hypothesized that the circadian gene Bmal1 might participate in the pathogenesis of diabetic cardiomyopathy and that such a connection would furnish new opportunities for mechanism-based diabetic cardiomyopathy therapeutics." (PMID 29113329, 2017). "Furthermore, it is conceivable that altered Bmal1 function resulting from disrupted circadian physiology may be a new mechanism that contributes to the prevalence of diabetic cardiomyopathy and other metabolic disorders." (PMID 29113329, 2017). "For instance, ATF4 in DCM promotes cardiac fibrosis and oxidative stress, while downregulation of Bmal1 induces mitochondrial dysfunction by promoting Bcl2/IP3R-mediated mitochondrial Ca2+ overload, leading to diabetic cardiomyopathy." (PMID 38664790, 2024).
diabetic retinopathy (3 papers, 2022 to 2025). "A similar observation was noted in an animal model of diabetic retinopathy, where loss of Bmal1 ameliorates retinal pathologies associated with diabetic retinopathy like the thinning of the retina and upregulation of molecular markers for DR46." (PMID 35933488, 2022). "The deficiency of the clock gene Bmal1 may facilitate the progression of diabetic retinopathy from NPDR to PDR, while its normal expression is likely to mitigate this pathological process." (PMID 41243864, 2025). "Moreover, Bmal1 gene is believed to be a pathologic cofactor of the diabetic retinopathy (DR), age‐related macular degeneration (AMD), premature aging and refractive myopia." (PMID 41243864, 2025). "Additionally, dysregulation of Bmal1 has been detected in retinopathies such as age‐related macular degeneration (AMD) and diabetic retinopathy (DR), in which altered circadian rhythms may disturb the retinal pathophysiological process." (PMID 41243864, 2025).
disc degeneration (3 papers, 2016 to 2024). "Further investigations on the contribution of BMAL1 in progression of disc degeneration are under way." (PMID 27049729, 2016). "Therefore, our study is the first to confirm that excessive mechanical loading dampens the IVD circadian rhythm and inhibits BMAL1 expression, finally leading to disc degeneration." (PMID 35217644, 2022). "We have shown that there is an interaction between BMAL1 and RORα and they modulate HIF-1α activity as well as ECM homeostasis and perturbation in circadian clock genes results in disc degeneration." (PMID 38510179, 2024).
esophageal cancer (3 papers, 2016 to 2024). A primary or metastatic malignant neoplasm involving the esophagus. "Since cancer progression is associated to reduced BMAL1 and PER2 oscillations, it will be important to determine whether more malignant esophageal cancer epithelial cells are characterized by additional modifications of clock related genes and how the circadian clock is impacted." (PMID 33810377, 2021). "The esophageal cancer cells were negatively isolated by MACS and subjected to RT-qPCR to detect the expression of circadian clock molecule mRNA, including NFIL3, Per1, Per2, Bmal1, Cry1, Cry2, Clock and Npas2." (PMID 26898709, 2016).
head and neck squamous cell carcinoma (3 papers, 2019 to 2022). A squamous cell carcinoma that arises from any of the following anatomic sites: lip and oral cavity, nasal cavity, paranasal sinuses, pharynx, larynx, and salivary glands. "Beside PER, also BMAL1 has been suggested to play a role in head and neck squamous cell carcinoma, being dependent on the oxidation of the tumor suppressor gene PTEN over the mTOR pathway." (PMID 30760278, 2019). "In comparison to the pericarcinomatous tissue of head and neck squamous cell carcinoma (HNSCC) patients, clock genes Bmal1, Pers, and Crys, especially Cry2, showed a downward trend in cancer tissue." (PMID 36467684, 2022).
hypertriglyceridemia (3 papers, 2013 to 2024). A laboratory test result indicating elevated triglyceride concentration in the blood.
Hypoinsulinemia (3 papers, 2020 to 2024). A decreased concentration of insulin in the blood. "Disruption of CLOCK and BMAL1, components of the circadian clock, results in hypoinsulinemia." (PMID 38731926, 2024).
lung adenocarcinoma (3 papers, 2016 to 2023). A carcinoma that arises from the lung and is characterized by the presence of malignant glandular epithelial cells. "In a recent study, the overexpression of CRY2, BMAL1, and RORα and the underexpression of Timeless and NPAS2 were associated with a favorable prognosis of lung adenocarcinoma." (PMID 38067152, 2023).
memory impairment (3 papers, 2023 to 2024). "Apart from DA signaling, Bmal1 deletion in mice was shown to result in activation of astrocyte proliferation, causing the development of abnormal pathological phenotypes such as memory impairment and hyperactivity." (PMID 36593479, 2023). "This study highlights a significant interplay between Bmal1, neuroinflammation, and memory impairment, mediated in part by neurotransmitters and receptors, particularly the 5-HT2C receptor." (PMID 39611170, 2024). "The absence of Bmal1 in microglia can also lead to varying degrees of memory impairment, although phagocytosis of these cells is increased." (PMID 36593479, 2023). "In the current study, we identified that pretreatment with melatonin significantly attenuated CRSD‐induced intermediate‐term and long‐term spatial learning and memory impairment, and this protective effect may attribute to the regulation of HDAC3 and Bmal1/Clock complex." (PMID 37721401, 2024).
nonalcoholic fatty liver disease (3 papers, 2024 to 2025). "Previous studies on the impact of BMAL1 on liver metabolism have mostly focused on external zeitgebers (such as restricted feeding) or non-alcoholic fatty liver disease (NAFLD) induced by a high-fat diet (HFD)." (PMID 38892255, 2024).
pancreatic ductal adenocarcinoma (3 papers, 2018 to 2024). An infiltrating adenocarcinoma that arises from the epithelial cells of the pancreas. "One studysuggested that human pancreatic ductal adenocarcinoma could be predictedby BMAL1 expression." (PMID 39072055, 2024). "In fact, immunohistochemistry analysis of Bmal1 in tumor tissues from 87 patients with pancreatic ductal adenocarcinoma showed lower levels of this protein compared with adjacent non-tumor tissues and low Bmal1 expression was associated with tumor progression and poor prognosis." (PMID 33042011, 2020).
pneumococcal infection (3 papers, 2019 to 2022). Infections with bacteria of the species streptococcus pneumoniae. "Surprisingly, myeloid Bmal1 deficiency was also found to confer protection against pneumococcal infection that was attributed to increased motility and phagocytic activity of Bmal1 deficient macrophages." (PMID 36430199, 2022). "It is important to note that our data revealing the response to pneumococcal infection are surprising, as previously work has shown that loss of BMAL1 in the myeloid lineage results in increased inflammatory responses to bacterial mimics, such as lipopolysaccharide." (PMID 31900362, 2020). "We have previously reported that the up-regulation of neutrophil influx in mice lacking a clock in the pulmonary epithelium (Ccsp-Bmal1−/−) does not confer an advantage in bacterial clearance after Streptococcus pneumoniae infection." (PMID 29965797, 2019).
pneumococcal pneumonia (3 papers, 2020 to 2022). A febrile disease caused by STREPTOCOCCUS PNEUMONIAE. "Here we show that loss of the core clock protein BMAL1 in macrophages confers protection against pneumococcal pneumonia." (PMID 31900362, 2020). "The striking observation that loss of the central clock gene Bmal1 resulted in a major protective effect against bacteraemia in pneumococcal pneumonia was unexpected, as most circadian disruptions impair fitness." (PMID 31900362, 2020). "This is in contrast to the beneficial effects seen with BMAL1 loss in Pneumococcal pneumonia, where the absence of BMAL1 allows augmented inflammatory action." (PMID 35880253, 2022). "As we had previously observed striking temporal regulation of pneumococcal pneumonia, which was not explained by Bmal1 deletion in the club cell, we returned to this model to determine how myeloid timekeeping impacted macrophage antibacterial function." (PMID 31900362, 2020). "However, macrophages lacking BMAL1 showed increased motility and phagocytic function, conferring protection against pneumococcal pneumonia." (PMID 36293015, 2022).
preeclampsia (3 papers, 2024 to 2025). Preeclampsia is a hypertensive disorder of pregnancy that is characterized by new-onset hypertension with proteinuria presenting after 20 weeks of gestation, and depending on mild or severe forms may initially present with severe headache, visual disturbances, and hyperreflexia. "Animal models with disrupted circadian clock genes—such as Bmal1 or Per2—exhibit impaired nocturnal BP regulation, heightened sympathetic tone, and increased vascular stiffness, all of which mimic features observed in gestational hypertension." (PMID 40649890, 2025).
pulmonary fibrosis (3 papers, 2016 to 2023). Chronic progressive interstitial lung disorder characterized by the replacement of the lung tissue by connective tissue, leading to progressive dyspnea, respiratory failure, or right heart failure. "In animals in which the clock was disrupted in adulthood by inducing global deletion of the core clock gene Bmal1 (Bmal1creERT/+ versus control Bmal1creERTneg) had significantly worse injury and more lung fibrosis than creneg littermates." (PMID 37463053, 2023). "In animal models of pulmonary fibrosis, BMAL1 expression was also significantly higher in adenovirus-TGF-β1-infected mice than in the control group." (PMID 26753996, 2016). "We propose that the cell-intrinsic clock machinery and the expression of specific clock genes, such as BMAL1, could be crucial in the understanding of the biology of myofibroblast, a key player in pulmonary fibrosis as well as tumor progression." (PMID 26753996, 2016). "However, it is still largely unknown whether clock genes, especially BMAL1, are involved in the development of lung fibrosis." (PMID 26753996, 2016). "Our findings indicate that inhibition of BMAL1 expression prevents not only EMT but also FMD, two major differentiation processes involved in the pathophysiology of pulmonary fibrosis as well as stromal support during tumor progression." (PMID 26753996, 2016).
rheumatoid arthritis (3 papers, 2017 to 2022). A chronic, systemic autoimmune disorder characterized by inflammation in the synovial membranes and articular surfaces. "In light of our findings, we suggest that this enhanced BMAL1 expression in rheumatoid arthritis may in fact act to dampen inflammation." (PMID 30612576, 2019).
temporal lobe epilepsy (3 papers, 2021 to 2025). A localization-related (focal) form of epilepsy characterized by recurrent seizures that arise from foci within the temporal lobe, most commonly from its mesial aspect. "Patients with temporal lobe epilepsy undergoing surgical resection of epileptic foci have shown decreased levels of BMAL1 in the hippocampal dentate gyrus." (PMID 36161152, 2022). "Moreover, BMAL1 regulates NPC differentiation that plays a part in the severity of neurodegeneration in temporal lobe epilepsy." (PMID 41440117, 2025). "In patients with hippocampal sclerosis, a common pathology in temporal lobe epilepsy, levels of BMAL1 and PCDH19 are significantly lower compared to patients without sclerosis; however, whether these molecular changes were due to seizure activity or the sclerotic lesion itself are unclear." (PMID 36161152, 2022). "However, the molecular mechanism of brain and muscle Arnt-like protein 1 (Bmal1), one of the core clock genes, in the epileptogenesis and seizures of temporal lobe epilepsy (TLE) remain unclear." (PMID 34261484, 2021). "Like CLOCK and BMAL1, expression of REV-ERBα is similarly dysregulated in patients with temporal lobe epilepsy." (PMID 36161152, 2022).
thyroid cancer (3 papers, 2021 to 2023). "We found that the mRNA expression of CLOCK and BMAL1 in thyroid carcinoma tissues (PTC) was significantly higher than that in benign and normal tissues, while the expression of CRY2 was decreased, indicating that circadian biological rhythm was involved in the occurrence of the disease." (PMID 34211057, 2021). "They found up-regulation of BMAL1 and the downregulation of CRY2 in tissues sampled from well-differentiated thyroid cancer." (PMID 36293065, 2022). "In the immunohistochemical experiment, the CLOCK and BMAL1 were dramatically stained in thyroid carcinoma but not in benign groups, while other genes were in low levels." (PMID 34211057, 2021). "CLOCK and BMAL1 were dramatically expressed in thyroid carcinoma but not in benign group, while other genes were in low levels of each group." (PMID 34211057, 2021). "Therefore, if it were consistently found in the reviewed studies that BMAL1, CLOCK and NPAS2 were upregulated in thyroid carcinoma, the suppressors of activity of BMAL1, CLOCK and NPAS2 (CRYs, DECs, and PERs) would be expected to be downregulated in this carcinoma." (PMID 37489438, 2023).
Ventricular arrhythmia (3 papers, 2022 to 2025). "Specific knockout of the Bmal1 gene in myocardial cells can lead to loss of tissue repolarization, sinus bradycardia, prolonged QRS duration, and increased frequency of ventricular arrhythmias (VA)." (PMID 40141370, 2025).
vitiligo (3 papers, 2020 to 2024). Generalized well circumscribed patches of leukoderma that are generally distributed over symmetric body locations and is due to autoimmune destruction of melanocytes. "We reported a significant circadian gene expression in vitiligo patients compared to control, with more detection rate of the BMAL1 T/C genotype." (PMID 38236441, 2024). "A significant increase in circadian gene expression in non-segmental vitiligo patients was observed, with more detection of the BMAL1 T/C genotype (92%) than the T/T genotype." (PMID 38236441, 2024).
abortion (2 papers, 2017 to 2022). the ending of pregnancy by removing a fetus or embryo before it can survive outside the uterus. "Recently, the expression of BMAL1 was demonstrated to be decreased in the endometrium of women suffering from recurrent spontaneous abortion." (PMID 35886985, 2022). "Recently, it was demonstrated that the expression of BMAL1 was decreased in the endometrium of women suffering from recurrent spontaneous abortion." (PMID 35886985, 2022). "We examined the expression of BMAL1 and downstream factors using human villous specimens collected from sporadic abortion (SA) patients and RSA patients in comparison with villous from women undergoing induced abortion (IA) with nonmedical causes." (PMID 29163762, 2017).
acute kidney injury (2 papers, 2025 to 2026). Sudden and sustained deterioration of the kidney function characterized by decreased glomerular filtration rate, increased serum creatinine or oliguria. "In summary, the function of the circadian rhythm gene Bmal1 varies among different acute kidney injury (AKI) models, sometimes exhibiting opposing effects in these situations." (PMID 39858471, 2025). "In particular, Bmal1 offers protective effects in various cases of drug-induced acute kidney injury, with overexpression of the gene showing potential to mitigate these injuries." (PMID 39858471, 2025). "Furthermore, circadian rhythms were shown to influence cisplatin-induced acute kidney injury, potentially due to fluctuations in Bmal1 expression." (PMID 39858471, 2025). "However, there is a lack of clinical research on how modulating circadian rhythms or directly regulating the BMAL1 gene can alleviate acute kidney injury or fibrosis." (PMID 39858471, 2025). "However, the role of BMAL1 in the repair process following acute kidney injury (AKI) remains unclear; therefore, this study aimed to elucidate its role in kidney repair following ischemia-reperfusion injury (IRI)." (PMID 42123667, 2026).